MMP1 (matrix metallopeptidase 1)
Diseases named in the same sentence as MMP1 in open-access papers (continued):
Sharing a sentence is not in itself a finding about the gene and the disease.
lung adenocarcinoma (17 papers, 2016 to 2026). A carcinoma that arises from the lung and is characterized by the presence of malignant glandular epithelial cells. "MMP1 has been already reported to cause resistance of lung adenocarcinoma to EGFR-TKIs through mTOR pathways." (PMID 35480306, 2022). "The migration and invasion potential in lung adenocarcinoma cells is promoted by a few MMP proteins, for example MMP1 has been associated to migration and invasion in lung adenocarcinoma resistant to epidermal growth factor receptor tyrosine kinase inhibitors (EGFR-TKI)." (PMID 34356991, 2021). "Additionally, the mTOR pathway is associated with induction of MMP-1 expression in lung adenocarcinoma, including EGFR-TKI–resistant cells." (PMID 29463039, 2018). "The fusion of human serum albumin with human lactoferrin (hLF-HSA) exerts strong anti-migratory effects in human lung adenocarcinoma cells through matrix metalloproteinase 1 (MMP1) downregulation." (PMID 41873731, 2026). "In this tumor PDS, the differential expression of the CADM1 and the MMP1 genes was reversed compared to that observed across the TCGA lung adenocarcinoma analysis." (PMID 38067281, 2023). "And the results revealed that MMP1 was significantly upregulated in lung adenocarcinoma (LUAD) and lung squamous cell carcinoma (LUSC) compared with normal lung tissues (|log2 (Fold change) | > 2 and P < 0.01)." (PMID 32703314, 2020). "We also first reveal the significant positive correlation between MMP-1 expression in lung adenocarcinoma cells and smoking history and the subtype of invasive mucinous adenocarcinoma." (PMID 29463039, 2018). "We compared the migration ability of PC9/ER, which was EGFR-TKI–resistant lung adenocarcinoma cells with a high expression of MMP-1, and PC9/6m using a wound healing assay and migration assay for 24 h." (PMID 29463039, 2018). "The present study is the first to examine the significance of MMP-1 in EGFR-TKI–resistant lung adenocarcinoma." (PMID 29463039, 2018). "In line with previous studies and our current in vitro studies, the clinical data analysis demonstrates that the expression of MMP1 correlates with the development, recovery, and survival of lung adenocarcinoma patients." (PMID 27391090, 2016). "Clinical data analysis reveals that the expression of MMP1 correlates with the clinical features and outcome of lung adenocarcinoma." (PMID 27391090, 2016). "After the identification of MMP1 as the downstream gene of PRAME, we further analyzed the clinical relevance of MMP1 in lung adenocarcinoma using the clinical data of lung adenocarcinoma patients." (PMID 27391090, 2016). "Taken together, our data suggest that PRAME serves as a tumor suppressor of lung adenocarcinoma via downregulating E-cadherin and MMP1-mediated migration, leading to the inhibition of EMT." (PMID 27391090, 2016). "Both the recurrence and the dead of lung adenocarcinoma patients at 5 years correlated with the expression of MMP1." (PMID 27391090, 2016). "In lung adenocarcinoma, high expression of CCL20, IL23A, MMP1 and MMP3 was significantly associated with poor patient prognosis, whereas high expression of FOS, HLA-DPA1, HLA-DPB1, HLA-DQA1, HLA-DQB1 and HLA-DRA was significantly associated with improved patient prognosis." (PMID 40016789, 2025). "Based on the limited studies, FAM198B mainly acts as a tumor suppressor gene to take effects, for example, FAM198B blocks ERK-mediated MMP-1 expression to prolong survival and inhibit metastasis in lung adenocarcinoma, and our study provides evidence for this discovery." (PMID 36158685, 2022). "Additionally, immunohistochemical studies using 89 cases of lung adenocarcinoma demonstrate that high expression of MMP-1 is significantly correlated with poor prognosis and factors such as smoking history and the subtype of invasive mucinous adenocarcinoma." (PMID 29463039, 2018).
lung adenocarcinoma (continued). "To conclude, this study is the first to reveal that MMP-1 plays an important role in the migration and invasion abilities of EGFR-TKI–resistant lung adenocarcinoma cells, and the mTOR pathway is associated with the induction of MMP-1 expression in these cells, resulting in a poor prognosis." (PMID 29463039, 2018). "Conversely, the tendency for a positive correlation between MMP-1 expression in lung adenocarcinoma cells and a pleomorphic subtype could be because lung adenocarcinoma with a pleomorphic subtype has a high ability for invasion." (PMID 29463039, 2018). "The mRNA levels of the MMP-1 gene in two EGFR-TKI–resistant lung adenocarcinoma cells (PC9/GR and PC9/ER) were significantly higher than those in EGFR-TKI–sensitive cells (PC9/6m) (PC9/GR vs. PC9/6m, p = 0.0349; PC9/ER vs. PC9/6m, p < 0.0001; PC9/ER vs. PC9/GR, p < 0.0001)." (PMID 29463039, 2018). "This study aims to clarify the significance of MMP-1 in EGFR-TKI–resistant lung adenocarcinoma." (PMID 29463039, 2018). "Furthermore, we are first to reveal the significant positive correlation between MMP-1 status in lung adenocarcinoma cells and smoking history and the subtype of invasive mucinous adenocarcinoma, as found in this study." (PMID 29463039, 2018). "We subsequently studied the mechanism of MMP-1 induction in lung adenocarcinoma cells." (PMID 29463039, 2018). "Additionally, we immunohistochemically investigate the association between MMP-1 expression and clinicopathological factors in detail to reveal the clinical significance of MMP-1 in lung adenocarcinoma." (PMID 29463039, 2018). "Some previous reports have stated that MMP-1 promotes the invasion ability of cancer cells, including A549, a lung adenocarcinoma cell without EGFR mutation." (PMID 29463039, 2018). "The present study, therefore, hypothesizes that various activities of EGFR pathways associated with EGFR mutation and EGFR-TKI resistance could possibly change the expression levels of MMP-1 in EGFR-TKI–resistant lung adenocarcinoma and contribute to the development of EGFR-TKI resistance." (PMID 29463039, 2018). "To estimate the survival function of ISG15, MMP1, TRPA1, KRT19, and PLAU, we performed KM plotter analysis generated for groups of lung adenocarcinoma patients based on their expression levels." (PMID 35354498, 2022). "As we showed in our study, MMP1, MMP9 and MMP10 genes are elevated in human lung adenocarcinomas relative to normal tissue." (PMID 30988374, 2019). "We investigate the effects of MMP-1 on migration and invasion abilities and the mechanism of induction of MMP-1 in EGFR-TKI–resistant lung adenocarcinoma." (PMID 29463039, 2018). "To conclude, this study provides insights into the development of a possible alternative therapy manipulating MMP-1 and the mTOR signaling pathway in EGFR-TKI–resistant lung adenocarcinoma." (PMID 29463039, 2018). "Lung adenocarcinoma patients with high expression levels of ISG15, MMP1, TRPA1, KRT19, and PLAU (red line) were significantly associated with poor survival rates (log rank P value: 2.3e-07, 0.00034, 0.00037, 0.00057, and 0.023, respectively) as compared to those with low expression (black line)." (PMID 35354498, 2022). "Therefore, in this study, the focus is on the function of MMPs, especially MMP-1, in EGFR-TKI–resistant lung adenocarcinoma." (PMID 29463039, 2018). "The tendency for a negative correlation between MMP-1 expression in lung adenocarcinoma cells and a lepidic subtype could be because lung adenocarcinoma with a lepidic subtype has a low potential for invasion." (PMID 29463039, 2018). "The expression of MMP1 was significantly higher in lung adenocarcinoma than in normal lung tissue." (PMID 27391090, 2016). "However, the correlation between MMP-1 and EGFR-TKI–resistant lung adenocarcinoma has not been studied." (PMID 29463039, 2018).
Obesity (17 papers, 2013 to 2025). Accumulation of substantial excess body fat. "Genetic variants in the MMP1 gene were shown to be associated with obesity traits in the Korean, Taiwanese and Chinese populations." (PMID 37445827, 2023). "The contribution of MMP-1 on obesity development was also demonstrated in studies including ours showing an association between polymorphisms of the MMP-1 gene and BMI values." (PMID 34625635, 2021). "The association of MMP-1 levels and obesity was also verified by significant positive correlations between MMP-1 levels or MMP-1/TIMP-1 ratio and BMI/WC values in people with obesity." (PMID 34625635, 2021). "Remarkably, ST36+GB34-treated obese rats were almost completely rescued from the deleterious effect of obesity, with more effectiveness in preventing cartilage loss and reducing the total Mankin score and the expression of MMP-1 and MMP-13." (PMID 32724821, 2020). "In conclusion, we found that the association between MMP1 gene polymorphisms and MMP1 level was dependent on obesity status." (PMID 23497408, 2013). "We aimed to elucidate genetic determinants of inflammatory marker levels, including circulating MMP1, in Taiwanese, and their association with obesity." (PMID 23497408, 2013). "Furthermore, we found that genotypes/haplotypes around the MMP1 locus interacted with obesity to set the MMP1 level, with the association occurring predominantly in non-obese subjects." (PMID 23497408, 2013). "Altogether, this study demonstrates that TLR2 mediates collagen accumulation and pro-inflammatory cytokines’ activation in WAT during diet induced obesity, involving MMP1 and TIMP1 imbalanced expression." (PMID 37445827, 2023). "Obesity causes the rise of various inflammatory cytokines and matrix metalloproteinases (MMP) such as interleukin (IL)-1 β, IL-6, MMP-1, MMP-6 and MMP-13." (PMID 38033821, 2023). "Apart from tumor-free status, which had rare expression of MMP1, MMP1’s relationship with female gender and obesity needs further investigation." (PMID 35948625, 2022). "Despite the contradictory effect of MMP-1 on obesity, the majority of studies indicated increased levels of MMP-1 in obesity." (PMID 34625635, 2021). "MMP-1 seems to be involved in a process that facilitates the development of adipose tissue and, consequently, leads to obesity." (PMID 30245717, 2018). "The impact of MMP-1 (-519A/G, -1607 1G/2G), MMP-3 Lys45Glu (A/G), MMP-7 -181A/G, and MMP-12 -82A/G variants and plasma MMP levels on obesity and microvascular reactivity in Tunisians." (PMID 29317790, 2017). "Several studies reported an enhanced expression of MMP-1 in preadipocytes from obese subjects suggesting a role in ECM remodeling in obesity." (PMID 29317790, 2017). "We analyzed five closely linked SNPs located near MMP genes on chromosome 11q21-22 in an attempt to elucidate the genetic determinants of circulating MMP1 levels in Taiwanese and perform interaction analysis for obesity." (PMID 23497408, 2013). "Inflammation observed in obesity could be stimulant of MMP-1 levels and could be involved in adipose tissue remodeling during adipose tissue expansion in obesity." (PMID 34625635, 2021). "Particularly MMP-1, -2 and -9 seem to play a role in the activation or inhibition in tissue remodeling, cardiovascular diseases, and obesity, and they could be related with physical activity." (PMID 32598403, 2020). "MMP-1 is involved in tissue remodeling during adipose tissue expansion in obesity; however, it is uncertain whether plasma MMP-1 concentration varies depending on BMI." (PMID 30245717, 2018). "The aims of the current study were, therefore, to assess the impact of MMP-1-519A/G (rs1144393), MMP-1 -1607 1G/2G (rs1799750), MMP-3Lys45Glu (A/G) (rs679620), MMP-7 -181A/G (rs11568818), and MMP-12 -82A/G (rs2276109) polymorphisms on obesity status and its anthropometric indicators." (PMID 29317790, 2017).
Obesity (continued). "Subdividing people with obesity into MetsO and MHO, a positive correlation was also detected between MMP-1 and BMI values in both MetsO (r = 0.25, p = 0.03) and MHO (r = 0.28, p = 0.03)." (PMID 34625635, 2021). "In conclusion, our results demonstrated that MMP-1, MMP-3 and MMP-9 levels were correlated with several obesity-related parameters including BMI, WC, blood pressure and endothelial-dependent response." (PMID 34625635, 2021). "Previous candidate gene studies on obesity and its related traits have reported GLP1R in European Americans, TRHR in Mexican-Mestizos and MMP1 in Koreans." (PMID 29868124, 2018). "The goals of the current report were to explore the impact of MMP-1 (-519A/G; -1607 1G/2G), MMP-3 Lys45Glu (A/G), MMP-7 -181A/G, and MMP-12 -82A/G SNPs on the development of obesity and its severity among Tunisians." (PMID 29317790, 2017). "Among MMPs, MMP-1, MMP-3, MMP-7, and MMP-12 genes have been found to affect adipose tissue remodeling and obesity-related metabolic traits." (PMID 29317790, 2017). "In ANOVA modeling, leptin concentrations in SF and SOCS-3 expression in cartilage significantly explained levels of SF MMP-1 and MMP-3 in the obese but not in the non-obese group pointing to obesity-related association of leptin and SOCS-3 in OA pathophysiology." (PMID 27716333, 2016). "It has been suggested that macrophage accumulation in adipose tissue has a central role in stimulating MMP1 and MMP3 production by preadipocytes, mediated by IL1β and TNFα, supporting the role of macrophages in stimulating tissue remodeling during adipose tissue expansion in obesity." (PMID 23497408, 2013). "Further, since genotypes/haplotypes near MMP1 locus interact with obesity to set MMP1 levels, genetic determinants for MMP1 level may be different between obese and non-obese individuals." (PMID 23497408, 2013).
coronary heart disease (15 papers, 2009 to 2025). "T2DM is associated with the elevated blood level of MMP-1 which is positively correlated with coronary heart disease occurrence in these patients." (PMID 27781209, 2016). "Several groups have shown an association between the 1G/2G polymorphism in the MMP1 gene and coronary artery disease, myocardial infarction, and peripheral artery disease." (PMID 23497408, 2013). "In a publication from the ARIC group, plasma levels of TIMP-1 and MMP-1 were unrelated to increased risk of coronary artery disease whereas in Framingham, plasma TIMP-1 levels were positively associated with cardiovascular incidence and death." (PMID 23554968, 2013). "MMP1 is increased in atherosclerotic plaques and gene polymorphism is suggested to influence the risk of coronary heart disease." (PMID 23874591, 2013). "MMP-1 has been shown to play an important role in myocardial matrix degradation, which is associated with ischemic heart disease." (PMID 21453457, 2011). "In this study we report a positive association of MMP-1 serum levels with total plaque burden in a population of 260 patients who underwent CT-angiography for exclusion of coronary artery disease." (PMID 19751510, 2009). "Five biomarkers, GDF15, IL6, MMP1, MMP7, and TNFR2, were significantly associated with all 6 non-cancer aging-related conditions, mortality, mobility limitation, heart failure, coronary heart disease, stroke, and dementia." (PMID 39695064, 2025). "The plasma levels of MMP-1, MMP-7, MMP-8, MMP-9, and MMP-10 are elevated in patients with coronary artery disease (CAD), whereas those of MMP-2 and MMP-3 levels are decreased." (PMID 36142454, 2022). "A total of 90 patients with coronary artery disease (61% men, 58 ± 12 years), including 60 patients with STEMI and 30 patients with SIHD, were assessed within 24 h of admission, by measuring serum microRNAs, and serum MMP-1 and MMP-9." (PMID 39194717, 2024). "We therefore hypothesised MMP-1 and MMP-9 serum levels to be associated with non-calcified lesions as determined by CT-angiography in patients with coronary artery disease." (PMID 19751510, 2009). "In addition, increased serum levels of MMP-1 have been found in patients with coronary artery disease in some, but not all studies, with highest levels being present in patients with unstable angina." (PMID 19751510, 2009).
head and neck squamous cell carcinoma (15 papers, 2007 to 2025). A squamous cell carcinoma that arises from any of the following anatomic sites: lip and oral cavity, nasal cavity, paranasal sinuses, pharynx, larynx, and salivary glands. "High MMP1 expression was associated with a poor prognosis and immune cell infiltration, including Treg cells, in head and neck squamous cell carcinoma." (PMID 37667257, 2023). "In head and neck squamous cell carcinoma cells, silencing the MMP1 gene by siRNA significantly inhibits cell proliferation, migration, and invasion, and activates apoptosis through the EMT process." (PMID 40657637, 2025). "We found that high expression of MMP1 and AKT1 is associated with lower survival chances in patients with head and neck squamous cell carcinoma compared to low expression." (PMID 38706907, 2024). "ANGPTL4 has also been revealed to enhance anoikis resistance and tumor metastasis via the upregulation of MMP‐1 expression in head and neck squamous cell carcinoma." (PMID 36507553, 2023). "MMP1 is the most potential biomarker in head and neck squamous cell carcinoma according to our bioinformatic analysis." (PMID 35426219, 2022). "In this regard, MMP-1 expression has been reported to contribute to the progression of Head and neck squamous cell carcinomas (HNSCC) and the suggest metastatic phenotype of human breast and colorectal cancers, among others." (PMID 31921634, 2019). "Additionally, we have analyzed the correlation between MMP1 expression levels and the prognosis of head and neck squamous cell carcinoma patients through database analysis (with tongue squamous cell carcinoma comprising the majority, approximately 25.2%, from GDAC Firehose)." (PMID 38706907, 2024). "When cultured head and neck squamous cell carcinoma (HNSCC) cell lines with CAFs, cetuximab resistance was induced and elevated level of matrix metalloproteinase-1 (MMP-1) was detected, and the resistance can be reversed by using MMP inhibitor." (PMID 34095111, 2021). "In head and neck squamous cell carcinoma (HNSCC), PLAU1 facilitates HNSCC cell proliferation, invasion, and metastasis via interaction with MMP-1." (PMID 35333672, 2022).